NMT1 (N-myristoyltransferase 1)
Diseases named in the same sentence as NMT1 in open-access papers (continued):
Sharing a sentence is not in itself a finding about the gene and the disease.
lung cancer (5 papers, 2022 to 2025). A malignant neoplasm involving the lung. "Taken together, our data indicate that NMT1 is a novel therapeutic target in (KL/K)MUT lung carcinoma, an aggressive and therapy-resistant lung cancer subtype." (PMID 38949950, 2024). "Our data suggest that NMT1 is a potential therapeutic target in lung carcinomas with mutant KRAS and LKB1 and/or KEAP1 (KL/K)MUT, which are highly aggressive and resistant to current therapies, including immune checkpoint inhibitors." (PMID 38949950, 2024). "Among them, adenosine 5′-monophosphate (AMP)-activated protein kinase (AMPK) and mTOR are key molecules in the regulation of intracellular metabolism and important molecules related to NMT1 in lung cancer." (PMID 37140999, 2023). "For example, in lung cancer, NMT1 mRNA levels were 3.5-fold elevated in advanced (stage IV) patients compared to healthy individuals, suggesting that it may drive malignant transformation." (PMID 40335986, 2025). "In addition, significantly elevated NMT1 mRNA expression has been observed in lung cancer, and expression usually increases with disease progression, with NMT1 expression being 3.5-fold higher in patients with lung cancer than healthy individuals by stage IV." (PMID 37140999, 2023). "NMT1, which is upregulated in various cancers, including oral squamous cell carcinoma (OSCC), liver cancer, lung cancer, breast cancer (BrCa), osteosarcoma, and bladder cancer, is frequently associated with poor prognosis." (PMID 40335986, 2025). "Although both NMT1 and NMT2 are expressed in lung cancer cells, AMPK is only specifically regulated by NMT1." (PMID 37140999, 2023).
prostate carcinoma (4 papers, 2018 to 2024). A carcinoma that arises from epithelial cells of the prostate gland. "When analyzing pathways associated with colorectal and prostate cancers, we observed that miRNAs targeting both NMT1/2 and MetAP2 genes also regulate the expression of key genes involved in these pathways, including AKT1, GSK3B, BRAF, MAPK and many others." (PMID 29579063, 2018). "In prostate cancer, inhibition of NMT1 also blocks the scaffold function of Src kinase and prevents protein–protein interaction with the androgen receptor (AR), thus inhibiting androgen-independent AR activation." (PMID 37140999, 2023). "Suppression of NMT1 was found to induce cell cycle arrest, proliferation inhibition and malignant growth inhibition in prostate cancer." (PMID 37140999, 2023).
breast tumor (3 papers, 2018 to 2023). "Elevated expression and activity of NMT1 are observed to varying degrees in a variety of tumours (such as colon, lung and breast tumours)." (PMID 37140999, 2023). "Elevated expression and activity of NMT1 is observed to varying degrees in a variety of tumour types (e.g. colon, lung and breast tumours)." (PMID 37140999, 2023).
lymphoma (3 papers, 2020 to 2024). A malignant (clonal) proliferation of B- lymphocytes or T- lymphocytes which involves the lymph nodes, bone marrow and/or extranodal sites. "Subsequently, NMT1 activity has been confirmed as being essential for lymphoma cell survival in a genome-wide Crispr-Cas9 assay, strengthening the evidence for a role of NMT1 in hematologic tumours." (PMID 37140999, 2023). "Interestingly, the low NMT2 expression levels seen in lymphomas, leukemia and other cell lines were not compensated by an increase in NMT1 expression." (PMID 33093447, 2020).
bladder cancer (2 papers, 2023). "NMT1 is significantly upregulated in bladder cancer, and high NMT1 expression is linked to poor patient prognosis." (PMID 37143582, 2023). "The inhibitor B13 can abrogate the functions of NMT1 and suppress tumor growth, suggesting that targeting NMT1 is a potential treatment for bladder cancer." (PMID 37143582, 2023).
dementia (2 papers, 2018 to 2025). Loss of intellectual abilities interfering with an individual's social and occupational functions. "In fact, two of these proteins showed significant associations with stroke or dementia (FBLN3, HTRA1) in consistent direction and three were located within cSVD GWAS loci (FBLN3, HTRA1, NMT1), supporting the robustness of these findings." (PMID 41266628, 2025). "Since miR-137 targets NMT1/2 genes and particularly in dentate gyrus and hippocampus, it would be interesting to further investigate the dynamics of miR-137 and NMT in dementia patients with HIV." (PMID 29579063, 2018).
fungal infection (2 papers, 2018 to 2023). "The NMT1/2 and MetAP2 genes’ targeting miR-132-5p was found to be associated with fungal infection of human dendritic cells with Candida albicans and Aspergillus fumigatus and regulates immune responses through the interactions with FKBP1B, KLF4, and SPN genes." (PMID 29579063, 2018).
heart failure (2 papers, 2025). Inability of the heart to pump blood at an adequate rate to meet tissue metabolic requirements. "Dysregulation of NMT2, but not NMT1, has been linked to heart failure and cardiac hypertrophy." (PMID 40859030, 2025). "Although NMT1 and NMT2 share ~77% sequence identity, NMT2 in particular plays a significant role in cardiac remodeling and heart failure, with affected patients exhibiting up to a 60% decrease in cardiomyocyte NMT2 levels compared to healthy individuals." (PMID 40859030, 2025). "In addition, drugs targeting NMTs (NMT1 and NMT2) have been suggested to be potent senolytics and a target for treating or preventing various diseases such as cancer and heart failure." (PMID 40792619, 2025).
liver cancer (2 papers, 2021 to 2023). An epithelial or non-epithelial malignant neoplasm that arises from the liver. "In liver cancer cells, we have revealed that NUPs are more likely to be predominantly expressed than NDPs, because NUPs are less ubiquitinated than regulated by NMT1." (PMID 34136404, 2021). "Moreover, both NMT1 and AHSG were associated with the tumor stage, while RPL29 reversely correlated with the tumor stage in liver cancer." (PMID 34136404, 2021). "Only NMT1 was identified highly up-regulated in liver cancer compared to normal liver." (PMID 34136404, 2021). "Notably, patients bearing liver cancer with higher levels of NMT1 and AHSG had a worse survival rate than those with lower level ones." (PMID 34136404, 2021). "Expectedly, expressing exogenous NMT1 could reverse the effects by impaired expression of NMT1, either in human liver cancer cells or mouse liver." (PMID 34136404, 2021). "Targeting N-myristolyation and NMT1 might be helpful to treat liver cancer." (PMID 34136404, 2021). "Collectively, N-myristolyation by NMT1 suppresses anti-tumorigenic NDP, whereas it stimulates pro-tumorigenic NUP by interfering their ubiquitination to finally result in a pro-tumorigenic outcome in liver cancer." (PMID 34136404, 2021). "Trough statistical analysis in 301 liver cancer specimens showed a positive relationship between AHSG and NMT1, whereas a negative relationship between RPL29 and NMT1 were revealed, further demonstrating that NMT1 might oppositely regulate expression of NUP and NDP." (PMID 34136404, 2021). "Via tissue microarray assay (TMA), we further confirmed that NMT1 but not NMT2, another NMT member, was elevated in liver cancer." (PMID 34136404, 2021). "Here, N-myristolyation and its enzyme NMT1, but not NMT2, were found to be critical in liver cancer." (PMID 34136404, 2021).
pancreatic cancer (2 papers, 2016 to 2022). "Our findings suggest that NMT1 is a novel therapeutic target in pancreatic cancer and warrants further investigation of tris DBA as a potential novel treatment for pancreatic carcinoma." (PMID 27438140, 2016). "Here we demonstrated that tris DBA, an inhibitor of NMT1 is effective at reducing growth and metastasis of pancreatic cancer in vivo, indicating that NMT1 may be a novel therapeutic target in pancreatic cancer." (PMID 27438140, 2016). "Importantly, tris DBA decreased pancreatic cancer cell migration in response to a gradient of soluble factors (chemotaxis), at least in part by decreasing the ability of cancer cells to elaborate cilia in an NMT1-dependent and SFK-independent manner." (PMID 27438140, 2016). "We propose that NMT1 is a novel regulator of cilia formation and tris DBA palladium a novel inhibitor of cilia formation and metastasis in pancreatic cancer." (PMID 27438140, 2016).
Parkinson disease (2 papers, 2020 to 2023). A progressive degenerative disorder of the central nervous system characterized by loss of dopamine producing neurons in the substantia nigra and the presence of Lewy bodies in the substantia nigra and locus coeruleus. "The loci within these eQTL scores have been reported to regulate expression of genes involved in various brain-related processes and disorders, such as neurite outgrowth and Parkinson’s disease (DCAKD, SLC35A4, SEC14L4, SRA1, NMT1, CPNE1, PLEKHM1, UBE3C)." (PMID 32066731, 2020).
rheumatoid arthritis (2 papers, 2023 to 2025). A chronic, systemic autoimmune disorder characterized by inflammation in the synovial membranes and articular surfaces. "In addition, NMT levels and activity are reduced in T-cells derived from rheumatoid arthritis patients, and recent research has linked NMT1 SNPs and reduced NMT1 expression to white matter hyperintensity (WMH) and stroke in the brain." (PMID 40451428, 2025). "In rheumatoid arthritis (RA), T cell deficits in NMT1 can lead to inflammation in synovial tissue due to impaired lysosomal transfer and AMPK activation." (PMID 37143582, 2023).
breast adenocarcinoma (1 paper, 2021). "These mAbs were used to perform immunohistochemical analysis of the abundance and distribution of NMT1 and NMT2 in normal breast epithelial samples and a large cohort of primary breast adenocarcinomas from the BCIRG001 clinical trial (n = 706)." (PMID 33398478, 2021).
chronic myeloid leukemia (1 paper, 2024). "To investigate the role of NMT1, we bypassed the essential dependency of NMT1 on cells by creating a doxycycline-inducible NMT1 knockout system that regulates the expression of NMT1 gRNA in near-haploid chronic myeloid leukemia (CML) HAP1 cells constitutively expressing Cas9." (PMID 38715059, 2024).
coronary artery disease (1 paper, 2024). "For example, among the candidate genes were known susceptibility loci for diabetes (PTPN22, CEP68, RREB1, TCF7L2), coronary artery disease (PSRC1, UNC5C, LPLA), depression (MAD1L1, YLPM1) and insomnia (NMT1)." (PMID 38541061, 2024).
cutaneous melanoma (1 paper, 2019). A primary melanoma arising from atypical melanocytes in the skin. "In cutaneous melanoma, we found that Tris DBA palladium inhibits N-myristoyltransferase 1 (NMT1) and blocks tumor growth in vivo." (PMID 31320995, 2019).
gastric cancer (1 paper, 2023). A primary or metastatic malignant neoplasm involving the stomach. "N-myristoyltransferase 1 (NMT1) has been implicated in many cancers, but its association with gastric cancer remains to be clarified." (PMID 36967718, 2023).
glioma (1 paper, 2018). A benign or malignant brain and spinal cord tumor that arises from glial cells (astrocytes, oligodendrocytes, ependymal cells). "Further analysis of the KEGG pathways enriched with miRNAs that targets only NMT1/2 gene transcripts revealed signaling pathways that regulate the pluripotency of stem cells, Hippo signaling pathway, estrogen signaling pathway and glioma." (PMID 29579063, 2018).
lupus (1 paper, 2018). "The B-cells of lupus patients were determined to have increased expression of miR-148, an NMT1-transcript-binding miRNA, and decreased expression of miR-1246, an NMT2-transcript-binding miRNA." (PMID 29579063, 2018).
lymph node metastasis (1 paper, 2017). "Finally, 12 probes were chosen for the final classification and associated with 14 genes including several lymph node metastasis-related genes, such as HOXD1, NMT1, and SEMA3E." (PMID 28951630, 2017).
metastatic prostate carcinoma (1 paper, 2018). A carcinoma that arises from the prostate gland and has spread to other anatomic sites. "The NMT1 targeting miR-675-5p, which is down regulated in metastatic prostate cancer, derives from the lncRNA H19." (PMID 29579063, 2018).
non-small cell lung carcinoma (1 paper, 2020). A group of at least three distinct histological types of lung cancer, including non-small cell squamous cell carcinoma, adenocarcinoma, and large cell carcinoma. "We generated H460 (non-small cell lung carcinoma) cells with reduced levels of NMT1 using lentiviral transduction of an NMT1-specific shRNA targeting sequence, followed by clonal selection in the presence of puromycin." (PMID 32686708, 2020).
squamous cell carcinoma (1 paper, 2025). A carcinoma arising from squamous epithelial cells. "Real-time quantitative PCR (qPCR) revealed that NMT1 mRNA levels were significantly elevated under hypoxia in three hypoxia-responsive squamous cell carcinoma cell lines (SCC9, SIHa, and KYSE-510), whereas NMT2 levels remained unchanged." (PMID 40605065, 2025).
thyroid cancer (1 paper, 2025). "Bioinformatic analyses revealed clinical associations between high Src and NMT1 expression and increased tumour recurrence in RAI-treated thyroid cancers indicating RAI-resistance." (PMID 40748136, 2025). "To our knowledge, this is the first report of NMT1 upregulation in thyroid cancer and we propose that high NMT1 expression predicts recurrence." (PMID 40748136, 2025). "This study reveals that myristolyated Src can repress RAIU via PBF and highlights NMT1 as a potential therapeutic target for the induction of RAIU in breast tumours and the restoration of NIS function in thyroid cancer." (PMID 40748136, 2025). "Given the availability of clinical data regarding radioiodide treatment, we first investigated NMT1, Src and PBF expression in thyroid cancer using The Cancer Genome Atlas (TCGA) and GEO datasets." (PMID 40748136, 2025). "Furthermore, we demonstrate that Src myristoylation, a lipid modification that promotes PM association, mediates RAIU repression via PBF in both breast and thyroid cancer cells, and RAIU is significantly induced by N-myristoyltransferase 1 (NMT1) inhibition." (PMID 40748136, 2025). "NMT1 inhibition significantly enhanced RAIU via Src and PBF in breast and thyroid cancer cells." (PMID 40748136, 2025).
thyroid tumour (1 paper, 2025). "High levels of both NMT1 and Src expression were associated with decreased DFS in RAI-treated patients, implying contribution to thyroid tumour progression." (PMID 40748136, 2025).
uveal melanoma (1 paper, 2019). A melanoma derived from melanocytes of the uveal tract. "In a uveal melanoma cells lines 92.1 and Mel290, we did not observe suppression of NMT-1 expression when treated for 24 hours with 2.7 μM Tris DBA." (PMID 31320995, 2019). "Surprisingly, we did not observe inhibition of NMT1 protein or activity in treated uveal melanoma cells." (PMID 31320995, 2019).
cancer (45 papers, 2007 to 2025). A tumor composed of atypical neoplastic, often pleomorphic cells that invade other tissues. "NMT1 is also associated with the development of other cancers, such as liver cancer, oral cavity cancer, brain tumours and gallbladder cancer, but the underlying mechanisms are still unclear." (PMID 37140999, 2023). "Taken together, the predicted data strongly support the association of miRNAs targeting NMT1/2 and MetAP2 genes to signaling pathways implicated in cancer and immune response." (PMID 29579063, 2018). "Our findings indicate that several miRNAs that target myristoylation related genes (NMT1/2 and MetAP2) are associated with cancer." (PMID 29579063, 2018). "Prompted by the highly prevalent loss of NMT2 expression in various cancers, especially in hematologic cancers, we sought to target the remaining NMT1 with the potent pan-NMT inhibitor PCLX-001 in a manner reminiscent of synthetic lethality, thereby sparing normal cells with two NMTs." (PMID 38715059, 2024). "The researchers proposed that the greater susceptibility of haematological cancer cells than other cancer cells to PCLX-001 may result from altered expression of NMT1 or NMT2." (PMID 37140999, 2023). "Dysregulation of NMT1 activity is implicated in cancer and stem cell differentiation." (PMID 29579063, 2018). "Association with poor outcomes is considered to be due to aberrant Src activation, leading to increased cancer cell metabolism, cancer metastasis and drug resistance, presenting NMT1 as a potential therapeutic target." (PMID 40748136, 2025). "These evidences consistently support NMT1 as a prognostic biomarker across cancer types and a potential therapeutic target." (PMID 40335986, 2025). "Inhibition of NMT1 leads to mitochondrial dysfunction and energy crisis, ultimately leading to cancer cell death." (PMID 40335986, 2025). "NMT1 is overexpressed in various tumor types and has been considered a cancer therapeutic target for years." (PMID 38949950, 2024). "Hematologic cancers had a higher dependency on NMT1 (average score of -1.033 ± 0.037) than other cancer types." (PMID 38715059, 2024). "Both human NMT isozymes, NMT1 and NMT2, are expressed in most tissues, and have been implicated in the development and progression of diseases including cancer, epilepsy, Alzheimer’s disease, and Noonan-like syndrome." (PMID 38206309, 2024). "Our results confirm the requirement of NMT1 for cell survival, and genetically validated the pharmacological targeting of NMTs with an NMTI for cancer therapy, especially in cancers with a highly prevalent loss of NMT2." (PMID 38715059, 2024). "Overall, while NMT2 loss initially appeared to be a significant component of NMTI sensitivity, cancer cell dependency on NMT1 for survival is even more important, particularly in NMT2-deficient cancer cells." (PMID 38715059, 2024). "Overall, although our data showed that NMT2 loss is an important component of PCLX-001 sensitivity, cancer cell dependence on NMT1 for survival was even more important, particularly in NMT2-deficient cancer cells." (PMID 38715059, 2024). "Here, gain- and loss-of-experiments and a series of in vitro and in vivo assays illustrated that NMT1 overexpression contributes to HCC cancer progression through the myristoylation of downstream substrates and the activation of key signaling pathways." (PMID 36617552, 2023). "Nmt1 has been considered a promising therapeutic target for its high expression in numerous cancer cells (40, –, 42)." (PMID 36541770, 2023). "As a consequence, selective inhibition of NMT1 function to control malignancies is a new approach in the field of anti-cancer drugs." (PMID 37140999, 2023). "The relationship between N-myristoyltransferase-1 (NMT1), which functions as an oncogene in various cancers, and Lamtor1 has been emphasized in cancer biology by several groups." (PMID 37173755, 2023).